CSNK1D (casein kinase 1 delta)
Diseases named in the same sentence as CSNK1D in open-access papers (continued):
Sharing a sentence is not in itself a finding about the gene and the disease.
bladder cancer (2 papers, 2020 to 2025). "Our results demonstrate that expression of the CSNK1D gene, which codes for CK1δ, is upregulated in superficial and infiltrating bladder cancer patients in two independent datasets." (PMID 32282334, 2020). "In the current study, we reported that mRNA levels of CSNK1D, the coding gene of CK1δ, are upregulated in both of superficial and invasive bladder cancers by analyzing two independent datasets." (PMID 32282334, 2020). "The results demonstrated that the gene expression of CSNK1D was upregulated in superficial and infiltrating bladder cancer patients." (PMID 32282334, 2020). "Our results here demonstrated that CSNK1D was upregulated in superficial and infiltrating bladder cancer patients from two independent datasets." (PMID 32282334, 2020).
gastric cancer (2 papers, 2018 to 2021). A primary or metastatic malignant neoplasm involving the stomach. "Among the gastric cancer patients, all the 15 overlapping genes appear to be isolated from each other, whereas among the controls, three gene pairs (SPINT1 and GMDS, GMDS and TNRC18, and CSNK1D and RNF19B) are connected." (PMID 33596182, 2021).
glioblastoma (2 papers, 2023 to 2025). The most malignant astrocytic tumor (WHO grade IV). "Abnormal expression and functional defects of CSNK1D are closely associated with the development and progression of various cancers, including melanoma, breast, glioblastoma and colon cancers." (PMID 37688771, 2023).
Hypertension (2 papers, 2020 to 2025). The presence of chronic increased pressure in the systemic arterial system. "In contrast, gene expression profiling of Spontaneously Hypertensive (SHR) rats, a genetic model of hypertension, demonstrated decreased expression of Bmal1 and Npas2, while Per1, Per2, Per3, Cry1, Cry2, Bhlhe41 and Csnk1D were all upregulated compared to naïve WKY controls." (PMID 33127986, 2020). "PNPLA7 and CSNK1D were upregulated in subordinate relative to dominant monkeys; PNPLA7 (patatin-like phospholipase), a regulator of adipocyte differentiation induced by metabolic stimuli, was shown to be upregulated in subjects with hypertension." (PMID 40709334, 2025).
lung carcinoma (2 papers, 2011 to 2022). "Although the mutation rate of CSNK1D is very low, a TCGA database analysis from certain tumor tissues and tumor cell lines clearly indicates genomic amplification of CSNK1D with the highest frequency in lung cancer and bladder/urinary tract cancer." (PMID 35267653, 2022).
melanoma (2 papers, 2019 to 2021). A malignant, usually aggressive tumor composed of atypical, neoplastic melanocytes. "In contrast, the CSNK1D-204 intron 2/3-derived ORF_CIN345 could be exclusively produced in melanoma (and maybe BCC or SCC), but not in surrounding stromal (healthy) cells, in order to maintain their malignant phenotype, or promote subsequent metastasis." (PMID 30795533, 2019). "The analysis focused only on CSNK1A1, CSNK1D, and CSNK1E, not on CSNK1G; CSNK1A1 alterations are dominant in clear cell renal cell carcinoma, and pancreas cancer, CSNK1D in liver and sarcoma, and CSNK1E in melanoma and liver." (PMID 33861751, 2021).
osteosarcoma (2 papers, 2021 to 2025). A usually aggressive malignant bone-forming mesenchymal neoplasm, predominantly affecting adolescents and young adults. "Moreover, in synchronized human U2OS osteosarcoma cells, which, in contrast to HeLa and HT1080 cells, possess a functional circadian oscillator, GAPVD1 was rhythmically associated with CSNK1D, and the strength of this interaction mirrored the binding of PER2 to CSNK1D." (PMID 33917494, 2021).
pancreas cancer (2 papers, 2021). "To investigate whether CSNK1D is required for GLI-driven tumor initiation in vivo, we performed xenograft experiments using GLI1-dependent A673 and GLI1-dependent PANC1 pancreatic cancer cells with concomitant inhibition of CSNK1D." (PMID 34439381, 2021).
triple-negative breast carcinoma (2 papers, 2018 to 2022). An invasive breast carcinoma which is negative for expression of estrogen receptor (ER), progesterone receptor (PR), and human epidermal growth factor receptor 2 (HER2). "To study the biological significance of CSNK1D expression in cancer cells, we first examined the effect of downregulated CSNK1D expression on proliferation and motility in the highly invasive triple negative breast cancer cell line MDA-MB-231." (PMID 30112110, 2018). "Similarly, CSNK1D has recently been identified as a novel drug target in Hedgehog/GLI-driven cancers, and silencing of CSNK1D attenuates the migration and metastasis of triple-negative breast cancer cells." (PMID 35300417, 2022). "We previously reported that CSNK1D is frequently amplified in triple negative breast cancer." (PMID 30112110, 2018).
bipolar disorder (1 paper, 2009). A disorder of the brain that causes unusual shifts in mood, energy, activity levels and the ability to carry out day-to-day tasks. "Note that one CSNK1D SNP was nominally associated with bipolar disorder, and the CSNK1D region on 17q achieved a maximum LOD score of 3.63 in a bipolar association study." (PMID 19166596, 2009).
breast tumors (1 paper, 2018). "Using in situ hybridization and immunohistochemistry, we confirm that the CSNK1D protein is highly expressed in primary breast tumor and matched metastatic lymph nodes." (PMID 30112110, 2018).
Ewing sarcoma (1 paper, 2021). A small round cell tumor that lacks morphologic, immunohistochemical, and electron microscopic evidence of neuroectodermal differentiation. "Genetic inhibition of CSNK1D was sufficient to abrogate colony formation in Ewing sarcoma cells." (PMID 34439381, 2021). "To corroborate that CSNK1D inhibition is a potent strategy to block GLI activation in SMOi-resistant settings, we performed chemical inhibition of CSNK1D in A673 and MHH-ES-1 Ewing sarcoma cells both showing SMO-independent GLI1 expression." (PMID 34439381, 2021). "In agreement with this notion, we show that genetic inhibition of CSNK1D diminishes the engraftment and tumor initiation capacity of GLI-dependent A673 Ewing sarcoma cells in immunodeficient mice." (PMID 34439381, 2021).
head and neck squamous cell carcinoma (1 paper, 2025). A squamous cell carcinoma that arises from any of the following anatomic sites: lip and oral cavity, nasal cavity, paranasal sinuses, pharynx, larynx, and salivary glands. "However, the biological functions of CSNK1D in head and neck squamous cell carcinoma (HNSCC) remain unclear." (PMID 41353440, 2025).
lymph node metastasis (1 paper, 2025). "Furthermore, we observed higher mRNA levels of CSNK1D in HNSCC patients with a higher pathological grade and at advanced clinical stage than those with the low grade and at an early stage, which was also observed in HNSCC patients with lymph node metastasis." (PMID 41353440, 2025).
medulloblastoma (1 paper, 2021). A malignant, invasive embryonal neoplasm arising from the cerebellum. "To analyze whether CSNK1D is involved in the regulation of oncogenic HH signaling, we performed an shRNA-mediated knockdown of CSNK1D in a HH responsive human medulloblastoma cell line (Daoy)." (PMID 34439381, 2021). "Of note, knockdown of CSNK1D was sufficient to reduce HH target gene and GLI1 protein expression in Daoy medulloblastoma cells, suggesting that CSNK1D is required for canonical HH signaling and HH target gene activation." (PMID 34439381, 2021).
microcephaly (1 paper, 2017). A congenital or acquired developmental disorder in which the circumference of the head is smaller than normal for the person's age and sex. "Recently, deletion of the human CSNK1D gene has been associated with a rare incidence of microcephaly and cardiovascular malformation." (PMID 28125685, 2017). "However, one 18.5-day old Csnk1d null embryo showed signs of microcephaly and others had features suggestive of focal CNS abnormalities." (PMID 28125685, 2017).
myocardial infarction (1 paper, 2022). Gross necrosis of the myocardium, as a result of interruption of the blood supply to the area, as in coronary thrombosis. "Meeting all the cutoff criteria across all the data set analyzed, MAN2A2/TNFRSF12A/SPP1/CSNK1D/PLAUR/PFKFB3/CXCL16 (herein we termed it MTSCPPC signature) was identified as a novel pathological signature of myocardial infarction and was used for subsequent analyses." (PMID 35163208, 2022).
opioid use disorder (1 paper, 2024). A substance-related disorder that involves the recurring use of opioids despite negative consequences. "Similarly, NR1D2, BMAL1, and CSNK1D rhythms were disrupted in opioid use disorder (OUD) and AUD patients compared to controls." (PMID 39766481, 2024).
oral squamous cell carcinoma (1 paper, 2025). "Only one study has reported on the expression of CSNK1D in the low T-stage oral squamous cell carcinoma, which involved an immunohistochemical assay." (PMID 41353440, 2025). "In conclusion, SB-203580 inhibited the growth of oral squamous cell carcinoma by regulating the function of CSNK1D." (PMID 41353440, 2025).
osteoporosis (1 paper, 2025). A condition of reduced bone mass, with decreased cortical thickness and a decrease in the number and size of the trabeculae of cancellous bone (but normal chemical composition), resulting in increased fracture incidence. "By targeting CSNK1D, it might be possible to develop therapies that more effectively prevent or treat osteoporosis, reducing fracture risk and improving bone health in affected individuals." (PMID 39612374, 2025).
periodontitis (1 paper, 2022). An acute or chronic inflammatory process that affects the tissues that surround and support the teeth. "Periodontitis in adults resulted in decreased levels of CSNK1D, RORA, CLOCK, DBP, NR1D1, ID2, and PER3 and a substantial increase in expression of FOS." (PMID 36472983, 2022).
Salmonella Infections (1 paper, 2021). Infections with bacteria of the genus SALMONELLA. "Apart from PPARδ, the work identifies new targets of KDM6B demethylase activity in the host upon Salmonella infection such as CSNK1D and DAAM1." (PMID 34696686, 2021).
spinal muscular atrophy (1 paper, 2021). A motor neuron disease that affect the muscles, and characterized by muscle weakness and atrophy resulting from progressive degeneration and irreversible loss of the anterior horn cells in the spinal cord (i.e., lower motor neurons) and the brain stem nuclei. "TDP-43 also regulates processing of Gemin6, a component of the Gem protein complex dysregulated in spinal muscular atrophy, and of CSNK1D, encoding one of the Ser/Thr Kinase CK-1 isoforms, which can phosphorylate up to 29 sites in TDP-43, some of these in response to stress." (PMID 34380047, 2021).
uterine corpus endometrial carcinoma (1 paper, 2023). A endometrial carcinoma (disease) that involves the body of uterus. "Our findings revealed that liver hepatocellular carcinoma and uterine corpus endometrial carcinoma had the highest mutation rates of CSNK1D (>5%)." (PMID 37688771, 2023).
cancer (24 papers, 2010 to 2025). A tumor composed of atypical neoplastic, often pleomorphic cells that invade other tissues. "Casein kinase 1δ (CK1δ, encoded by casein kinase 1 delta) (CSNK1D) is a serine/threonine protein kinase closely associated with cancer development." (PMID 41353440, 2025). "We also investigated the association between CSNK1D expression and immune checkpoint inhibitors in various cancers." (PMID 37688771, 2023). "In this study, we analyzed the genetic changes in the CSNK1D gene using the TCGA cancer dataset through the cBioPortal tool, which included mutations, structural variations, amplifications, and deep deletions." (PMID 37688771, 2023). "Our exploration encompassed analyzing the expression of CSNK1D mutations across various cancer types and their probable correlation with clinical results." (PMID 37688771, 2023). "We further examined the mutation rate of CSNK1D in cancer using the TIMER database, which showed that the mutation rate of CSNK1D was highest in UCSC (15/531) and COAD (9/406)." (PMID 37688771, 2023). "We employed univariate Cox regression analysis to explore the association between CSNK1D expression and overall survival (OS) in 33 types of cancer." (PMID 37688771, 2023). "The results of this study form the basis for the development of efficient CSNK1D inhibitors for the therapy of HH—GLI-associated cancers." (PMID 34439381, 2021). "Overall, this study sheds light on the pivotal role of CSNK1D in cancer development and progression and provides novel insights into its potential use as both a diagnostic and therapeutic target for diverse forms of cancer." (PMID 37688771, 2023). "Notably, high CSNK1D levels were positively associated with CD4_Tcells, Neutrophils, and NK_cells in almost all cancer types." (PMID 37688771, 2023). "List of selected mutations in CSNK1D and the respective cancer types." (PMID 31817920, 2019). "Various mutations of CSNK1D have been identified and reported for different types of cancer." (PMID 31817920, 2019). "In summary, our data indicated that CSNK1D promoted HNSCC cancer progression by increasing the nucleus entry of GLI1 and activating the hedgehog GLI1/BCL2 signaling pathway." (PMID 41353440, 2025). "The over-expression of CSNK1D is observed in various cancers, and in Group 3 and 4 MB, with high expression linked to poor survival." (PMID 40002179, 2025). "Our research has revealed that CSNK1D displays abnormal expression patterns in various types of cancer and holds great significance in cancer prognosis." (PMID 37688771, 2023). "Firstly, our objective was to investigate the immune characteristics of CSNK1D in the tumor microenvironment (TME) across various cancers." (PMID 37688771, 2023). "The research utilized various online resources and databases like UCSC, NCBI, GEPIA2, HPA, cBioPortal, SangerBox, UALCAN, and TCGA for analyzing CSNK1D expression, prognosis significance, immune features, and gene alterations in cancers." (PMID 37688771, 2023). "Heightened CSNK1D expression correlated with reduced overall survival and disease-free survival rates in different cancer patient cohorts." (PMID 37688771, 2023). "In conclusion, this study reveals the aberrant expression patterns of CSNK1D in various types of cancer and highlights its significant relevance to cancer prognosis." (PMID 37688771, 2023). "It is worth noting that our research has revealed a noteworthy positive correlation between the expression of CSNK1D and molecules involved in various cancer-related pathways across multiple cancer types." (PMID 37688771, 2023). "Overall, this research sheds light on the pivotal involvement of CSNK1D in cancer development and progression and provides novel insights into its potential as a diagnostic and therapeutic target for diverse forms of cancer." (PMID 37688771, 2023).
cancer (continued). "Our objective for this study was to thoroughly scrutinize the variations in CSNK1D found in cancer, utilizing the Cancer Genome Atlas (TCGA) and other datasets accessible to the public." (PMID 37688771, 2023). "Our results revealed a strong correlation between CSNK1D and stromal cells in the tumor microenvironment of these cancers." (PMID 37688771, 2023). "Our study sheds light on the potential role of CSNK1D as a crucial biomarker in cancer diagnosis and progression monitoring." (PMID 37688771, 2023). "In this section, we aimed to investigate the impact of CSNK1D expression on the prognosis of cancer patients using TCGA RNA-seq and clinical data." (PMID 37688771, 2023). "To investigate the relationship between CSNK1D and immune cells in various cancers, we utilized seven immune infiltration algorithms, namely EPIC, TIMER, IPS, QUANTIAEQ, xCell, MCPcounter, and CIBERSORT." (PMID 37688771, 2023). "Pancancer analysis indicates that the expression of CSNK1D was correlated to shorter DFS time in multiple cancer types, such as COAD and LIHC, and was dysregulated in various cancers, which was consistent previous reports." (PMID 35880088, 2022). "CSNK1D overexpression reinforced the sphere formation ability, while CSNK1D silencing downregulated the cancer stem cell-like property." (PMID 36460966, 2022). "Of note, genetic as well as pharmacologic inhibition of CSNK1D efficiently represses oncogenic GLI activity in cancer cells resistant to FDA-approved HH pathway inhibitors targeting the essential HH effector SMO." (PMID 34439381, 2021). "Inhibition of CSNK1D function reduces the malignant properties of so-called tumor-initiating cells, thereby limiting cancer growth and presumably metastasis." (PMID 34439381, 2021). "The cell migration was also significantly inhibited by SR-3029 in a dose dependent manner (Unpaired t test: P < 0.005 in the presence of 30 nM and 100 nM inhibitor), suggesting a role for CSNK1D in cancer cell migration." (PMID 30112110, 2018). "Ours results indicate that CSNK1D inactivation specifically prevents metastasis of cancer cells and correlates with increased tight junction proteins expression." (PMID 30112110, 2018). "Recent studies have indicated that casein kinase 1-epsilon (CK1ɛ) and casein kinase 1-delta (CK1δ) expression has a role in human cancers." (PMID 24557581, 2014). "CSNK1D can promote cancer development and progression through multiple mechanisms." (PMID 37688771, 2023). "Furthermore, abnormal expression of the CSNK1D gene has been reported in various cancers, and it is considered an important cancer-related gene that participates in biological processes such as tumor cell proliferation, migration, and invasion." (PMID 37688771, 2023). "Overall, our results suggest that CSNK1D expression plays a critical role in cancer prognosis, and its effects may vary depending on the cancer type." (PMID 37688771, 2023). "CSNK1D expression has also been found to be closely linked with TMB and MSI in several types of cancer, indicating its potential as a diagnostic and prognostic biomarker for cancer." (PMID 37688771, 2023). "Additionally, the stromal scores were negatively correlated with CSNK1D expression in all cancers (P < 0.05)." (PMID 37688771, 2023). "Thus, the CSNK1D gene has become a key focus of cancer research and provides a significant foundation for the development of novel cancer treatment strategies." (PMID 37688771, 2023). "Finally, pancancer analysis showed that higher expression of CSNK1D was correlated with shorter DFS time in multiple cancer types, such as COAD and LIHC, and was dysregulated in various cancers." (PMID 35880088, 2022). "Previous studies have reported that CSNK1D may have an involvement in the carcinogenesis of a variety of cancers." (PMID 36460966, 2022). "Gene expression and activity changes of CSNK1D have been observed in distinct cancers." (PMID 35814454, 2022).